HOXA7 (homeobox A7)
Diseases named in the same sentence as HOXA7 in open-access papers (continued):
Sharing a sentence is not in itself a finding about the gene and the disease.
tumor (24 papers, 2008 to 2025). "In ESCC, it has been shown that HOXA7 induces tumor-associated macrophage infiltration and M2 polarization by promoting CCL2 secretion." (PMID 39596630, 2024). "In the present study, the gene panel CDO1, SOX17, and HOXA7 showed the best diagnostic accuracy in the subgroup with tumor size 2.1-3 cm and decreased in subgroups with smaller tumor size, especially when the tumor size was less than 1 cm." (PMID 32138766, 2020). "The downregulated expression of HOXA7 in ccRCC and its lower expression being associated with poorer patients’ prognosis indicated that it might be a tumor suppressor in ccRCC." (PMID 36387262, 2022). "On the contrary, HOXA7 was downregulated in tumor tissues and regarded as a protective factor (hazard ratio <1), which were upregulated in the low-risk subgroup." (PMID 35342423, 2022). "The GSEA indicated that the tumor samples with elevated HOXA7 expression downregulated miRNA targets in ECM and membrane receptors, as well as metastatic brain tumor pathways, while the apoptosis pathway was upregulated." (PMID 35693013, 2022). "Overexpression of HOXA7 enhanced tumor growth as indicated by increased intensity of the bioluminescent signal." (PMID 35183163, 2022). "We discovered that HOXA7 was overexpressed in CRC and that high levels of HOXA7 were correlated with a greater incidence of metastasis, more aggressive tumor phenotype, and shorter overall survival time." (PMID 35183163, 2022). "It is found that HOXA7 and ferroptosis index are positively correlated while inhibiting tumor brain metastasis." (PMID 35693013, 2022). "Through comparative analysis between tumor tissues and their paired nonmalignant mucosa, we identified HOXA7 overexpression as a critical prognostic biomarker associated with poor outcomes in ESCC patients." (PMID 39596630, 2024). "We can speculate that dysregulation of HCP5 expression in LUAD patients may lead to tumor brain metastasis by downregulating HOXA7 by affecting miR-17-5p." (PMID 35693013, 2022). "Therefore, increased levels of HOXA7 and HCP5 were associated with the downregulation of tumor brain metastasis." (PMID 35693013, 2022). "As the quantity of circulating tumor DNA for detection is related to stage and tumor volume, we explored the diagnostic accuracy of the combination of best three genes (CDO1, SOX17, and HOXA7) according to tumor size." (PMID 32138766, 2020). "Through these additional analyses, we can confirm that Hoxa9 upregulation is essential for the leukaemic phenotype of BcorΔE9-10KrasG12D tumours, and Hoxa7 and Hoxb5 may also be important." (PMID 30902969, 2019). "In summary, we demonstrated that HOXA7 overexpression upregulated CXCL1 expression, facilitating the recruitment and infiltration of MDSCs into the KRAS mutant CRC tumor niche." (PMID 35183163, 2022). "To explain the potential effectiveness of the HCP5 /hsa-miR-17-5p/HOXA7 axis in LUAD at the clinical level, we performed qRT-PCR using available tumor samples from 29 LUAD patients." (PMID 35693013, 2022). "The transcript levels of HOXB1, HOXA7, HOXB5, HOXD8, HOXB9, HOXA9, and HOXA11 were significantly lower in ccRCC tumor tissues compared to adjacent normal tissues, which was consistent in both TCGA and ICGC cohorts." (PMID 36387262, 2022). "HOXA7, HOXA10 and HOXA13, which are highly expressed in LSCC tissues, have a weak positive correlation with tumor purity." (PMID 33763449, 2020). "The relative level of hematopoiesis gene (e.g., Hoxa5, Hoxa7, Evi1, and Meis124,25) mRNA expression was decreased in CXCR2−/− tumor-bearing mice." (PMID 31395859, 2019). "Down-regulated expression was observed for the tumor suppressor and inhibitor of WNT signaling CXXC4, and the differentiation inducing transcription factors, HOXA7 and HOXA9." (PMID 29100312, 2017).
tumor (continued). "In both tumor sets, some samples showed H3K27me3 enrichment along the entire length of the HOXA and HOXD clusters, but others demonstrated variability in H3K27me3 at the HOXA1 through HOXA7 loci and the proximal HOXD locus." (PMID 36759899, 2023). "In addition, the expression of both HOXA7 and HCP5 was positively correlated with FPI, suggesting a strong correlation between ferroptosis and tumor brain metastasis." (PMID 35693013, 2022). "Interestingly, while the combination of CDO1, SOX17, and HOXA7 showed the overall best performance in our patient cohort, the combination of CDO1, TAC1, and SOX17 had the best performance in the subgroup with tumor size less than 1.0 cm." (PMID 32138766, 2020). "Furthermore, three-gene combinations detected even the smallest lung nodules, with the combination of CDO1, SOX17, and HOXA7 having the overall best performance, while the combination of CDO1, TAC1, and SOX17 was best in tumor sizes less than 1.0 cm." (PMID 32138766, 2020).
blood disorders (1 paper, 2025). "Together, these findings demonstrate that Hoxa7-TPO cells represent a facile model for examining human blood disorders and for analyzing efficiently the gene regulatory networks that control platelets and RBC formation from MEPs." (PMID 40775216, 2025).
HOXA7 also shares sentences with these, for which no sentence is quoted: keloid (2 papers); acute leukemia (1); adenocarcinoma (1); astrocytoma (1); brain cancer (1); breast tumor (1); congenital heart defects (1); endocrine disorders (1); gastric cancer (1); Hutchinson-Gilford progeria (1); leukoplakia (1); lung adenocarcinoma (1); multiple myeloma (1); oesophageal adenocarcinoma (1); oligodendroglioma (1); pancreatic adenocarcinoma (1); pancreatic cancer (1); renal carcinoma (1); squamous cell carcinoma (1); squamous cell lung carcinoma (1); Thrombocytopenia (1); Umbilical hernia (1).